NF1 (neurofibromin 1)
Diseases named in the same sentence as NF1 in open-access papers (continued):
Sharing a sentence is not in itself a finding about the gene and the disease.
lung carcinoma (continued). "In addition, human KRAS‐mutant lung cancer cell lines harboring NF1 mutations (i.e., H2030 and H2347) showed marked sensitivity to glutaminase and PSAT1 inhibition, while those with WT NF1 (i.e., H23, H2009, and H1792) displayed less sensitivity." (PMID 31036704, 2019). "Therefore, there is evidence that suggest that NF1 mutations in lung cancer con also activate Ras signaling pathway, playing a key role in the incorrect signal transduction, proliferation and malignant transformation." (PMID 31867044, 2019). "While mutation in the E2F/NF1-e/c-Myb binding site (Le7 and 12) led to a marked reduction in the expression of the luciferase reporter in hematopoietic cell lines, their effect on luciferase expression in lung cancer cells was minor." (PMID 22253833, 2012). "On the basis of these findings, one can speculate that the risk for the development of primary lung carcinoma in NF-1 patients might be increased, at least in some patients, due to increased prevalence of deletions on chromosome arm 17 p." (PMID 20531996, 2009). "Our data were found in patients with unknown resistance to treatment, and although the number of patients was low and data were precursory, in the evolution of EGFR-mutated lung cancer, NF1 could be playing an unknown role in disease progress and resistance to targeted therapies." (PMID 35884384, 2022). "Therefore, concurrently using EGFR and MEK inhibitors might be superior to monotherapy for TKI-resistant NF1-mutated lung cancer." (PMID 33061844, 2020). "The RAS signaling pathway is constitutively activated in both the LL2 lung cancer model, through an activating RAS mutation, and the MPNST model, by the loss of NF1." (PMID 40563570, 2025). "According to the TGCA database, about 14%, 11%, and 9% of lung cancer possess mutations in Kelch Like ECH Associated Protein 1 (KEAP1), Neurofibromatosis type 1 (NF1), and Epidermal growth factor receptor (EGFR), respectively." (PMID 39596025, 2024). "This study was aimed to investigate the molecular, clinical characteristics, and prognostic features of NF1 gene in EGFR mutant lung cancer patients." (PMID 35702826, 2023). "Further verification found that six hub genes were screened in relation to lung cancer, including mTOR, NF1, CHD7, ETS1, IL-6, and COL1A1." (PMID 36211008, 2022). "Six hub genes were screened in relation to lung cancer, including mTOR, NF1, CHD7, ETS1, IL-6, and COL1A1." (PMID 36211008, 2022). "We chose NF1 as the downstream target for validation, as NF1 has previously been associated with lower urinary tract dysfunction and resistance to EGFR inhibition in lung cancer." (PMID 35130920, 2022). "In lung cancer models, reduced NF1 expression mediates resistance to EGFR therapy, and blocking MEK restores the response." (PMID 31906320, 2020). "Treatment of lung cancer with low levels of NF1 expression with MAP-ERK kinase (MEK) inhibitors can restore sensitivity to erlotinib and reverse erlotinib resistance." (PMID 33061844, 2020). "NF1 encodes for a negative regulator of KRAS and inactivation leads to EGFR inhibitor resistance in lung cancer." (PMID 31287991, 2019). "For every unit increase in the relative expression of NF1 gene, the odds of having lung cancer dropped by approximately 90% (OR = 0.1)." (PMID 27418131, 2016). "The use of a comprehensive cancer panel including genes with recurrent mutations in lung cancer, such as KEAP1 and NF1, would certainly be more efficient to identify patients for whom ctDNA follow-up would be possible." (PMID 28027313, 2016). "Among the three age-dependent markers, an increased relative expression of NF1 and WEE1 genes had a protective effect on subjects, whereas an increased relative expression of MDM2 gene was a risk factor for developing lung cancer." (PMID 27418131, 2016).
lung carcinoma (continued). "A review from Japan 20 years ago reported only 11 cases of NF-1 with lung cancer, and we interestingly were able to find 7 more cases up to now—without including the presented case—also from the Japanese literature." (PMID 23533906, 2013). "However, the association of lung cancer with NF-1 might be coincidental." (PMID 23533906, 2013). "We present a case of a 48-year-old man with NF-1 that manifested as carcinoma of lung, in order to discuss the linkage between these two entities." (PMID 20531996, 2009). "Moreover, lung cancers harboring EGFR mutations exhibit increased resistance to tyrosine kinase inhibitors (TKIs) such as Erlotinib and Gefitinib when NF1 levels are low." (PMID 39596025, 2024). "The NF1 gene represses the RAS signaling pathway, and its mutation or abnormal expression may lead to lung cancer." (PMID 36702236, 2023). "At present, the mechanism of NF1 mutations in lung cancer initiation and progression has not been explored." (PMID 35702826, 2023). "Whole‐exon sequencing showed that the mutation rate of the NF1 gene in lung cancer was 11%; it was enriched in samples otherwise lacking oncogene mutations." (PMID 35702826, 2023). "All 160 NF1 mutant sites were detected in our 135 NF1 mutant lung cancer patients." (PMID 35702826, 2023). "This was the largest sample size analysis for NF1 gene in East Asia lung cancer patients." (PMID 35702826, 2023). "However, there were 5 cases of RASA1 mutations among 59 NF1 mutation patients (8.5%), which indicated that the occurrence of RASA1 mutations is obviously related to the occurrence of NF1 mutations in lung cancer patients." (PMID 35702826, 2023). "This study was the largest comprehensive analysis for NF1 gene in East Asia lung cancer patients." (PMID 35702826, 2023). "The present study identified six hub genes that were related to lung cancer, including mTOR, NF1, CHD7, ETS1, IL-6, and COL1A1, which might be a potential target for lung cancer." (PMID 36211008, 2022). "In conclusion, the present study screened 46 DEMs in GSE17681 and 1029 DEGs in GSE18842 and identified six hub genes related to lung cancer, including mTOR, NF1, CHD7, ETS1, IL-6, and COL1A1, which might be potential targets for lung cancer." (PMID 36211008, 2022). "In addition, six hub genes that were related to lung cancer were identified as hub genes, including mTOR, NF1, CHD7, ETS1, IL-6, and COL1A1." (PMID 36211008, 2022). "NF1 is regarded as a tumor suppressor in lung cancer negatively regulates RAS signaling pathway." (PMID 32206449, 2020). "We found that compared to recurrence patients, Met, ALK, APC, PTEN, ERBB4, NF1, and other genes in recurrence-free patients never mutated, involving multiple tumor suppressor genes and lung cancer-driven genes." (PMID 31182981, 2019). "Importantly, reduced NF1 expression has been also demonstrated to confer resistance to EGFR inhibition in lung cancer." (PMID 31226844, 2019). "However, most patients with NSCLC show acquired resistance to EGFR‐TKIs, and low expression of NF1 is a mechanism of EGFR‐TKI resistance in lung cancer." (PMID 29493886, 2018). "Why, for example, are NF1 patients not predisposed to lung tumours given that at least 10% of all sporadic lung cancers have NF1 mutations ?" (PMID 28637487, 2017). "The evaluation of pulmonary involvement in NF-1 patients with low-dose chest CT in long intervals could be proposed in order to detect early development of lung cancer or interstitial lung disease." (PMID 23533906, 2013).
lung carcinoma (continued). "Finally, we included 10 well-known cancer-related genes (or their hotspot-containing exons) listed as most frequently mutated in lung cancer (BRAF,EGFR,ERBB2,HRAS,KRAS,MAP2K1,MET,NF1,NRAS, and RIT1) in the panel to serve as internal controls for highly mutated regions." (PMID 40867048, 2025). "Known lung cancer genes (EGFR, KRAS G12C, ALK, MET, RET) were found in 33 patients; 11 had genes relevant to both lung and other cancers (ERBB2, BRAF V600, NTRK), and 37 had genes typically linked to other malignancies (NF1, PIK3CA, PALB2, FGFR2B, FBX7, RAD51)." (PMID 40244261, 2025). "Deleterious NF1 mutations have been previously reported in non‐small‐cell lung cancer (NSCLC), but the genomic landscape of this molecular subgroup remains poorly characterized in the lung cancer population; the clinical outcomes of NF1 mutant NSCLC also remain unknown." (PMID 35702826, 2023). "Therefore, NF1 mutations should not always be considered a poor biomarker in lung cancer, similar to mutations in the KRAS gene." (PMID 35702826, 2023). "NF1 mutations should not always be considered a poor biomarker in lung cancer." (PMID 35702826, 2023). "Moreover, other pathogenic NF1 alterations were detected, such as the p.L792F variant, in all patients analyzed, but, although NF1 variants occur in lung cancer, their clinical significance is not well documented." (PMID 35884384, 2022). "For example, treatment of NF1-deficient lung cancers with map-ERK kinase (MEK) inhibitors restores sensitivity to erlotinib; and combining type II Rafi with an allosteric MEKI reliably prevents and overcomes acquired drug resistance in cancers with NF1 mutations." (PMID 34795217, 2021). "In contrast to the results of TCGA4,5, we detected low mutational frequencies of STK11, NF1, and BRAF were detected in LUAD and low mutational frequency of KEAP1 in both LUAD and LUSC, indicating the special molecular characteristics of Chinese lung cancer patients." (PMID 33219256, 2020). "Furthermore, Met, ALK, APC, PTEN, ERBB4, NF1, and other genes, involving multiple tumor suppressor genes and lung cancer-driven genes, did not mutate in recurrence-free patients when compared with recurrent patients." (PMID 31182981, 2019). "NF1 mutations occur in lung cancer but were not extensively explored." (PMID 31199580, 2019). "In addition, five of the genes that we identified in this study, CPEB4, DUSP6, NF1, RNF4, and STAT2, were previously proposed as prognostic markers for NSCLC, whereas changes in the expression of MCM4 and WEE1 were associated with lung cancer development." (PMID 27418131, 2016). "In lung cancer models, resistance to EGFR targeted therapy was mediated by NF1 expression, and blocking MEK restored the response." (PMID 35702826, 2023). "Moreover, NF1 mutations are not just considered as lung cancer driver genes." (PMID 35702826, 2023). "The Vorinostat/Sapanisertib combination was identified as a promising drug combination that kills NF1-mutant nervous system malignancies as well as NF1- and KRAS-mutant lung cancers." (PMID 33024443, 2020). "The information from the TCGA studies has highlighted the involvement of NF1 in both lung ADC and SqCC and served to improve our understanding of the genetic pathways that lead to lung cancer." (PMID 28637487, 2017). "One of the NF1-GIST patients died from disease progression, and the other died following lung cancer." (PMID 26511941, 2016). "However, the association of NF-1 with lung cancer is not common." (PMID 23533906, 2013). "Our results showed that NF1 mutations had no direct effect on OS in LUAD cases or LUSC cases, even in lung cancer patients without driver genes (EGFR mutations and ALK fusion)." (PMID 35702826, 2023). "Similar enrichments of SGMs were seen in other core TSGs such as RB1, NF1, and ARID1A and emerging TSGs such as MGA, a transcription factor of the MYC network that suppresses growth and invasion in cellular and mouse models of lung cancer." (PMID 37922356, 2023).
lung carcinoma (continued). "Analysis indicated that CDKN2A, FAT1, MSH6, ARID1A, KEAP1, NF1, and SMAD4 mutation was more recurrent in patients with ERBB2 SNV/indels within the kinase domain compared with non-kinase domain in lung cancer." (PMID 35911441, 2022). "In the old lung cancer group, there were genes significantly concurrent with actionable driver genes (CDKN2A, NF1): FAT1, LRP1B, ARID2 with CDKN2A; EPHB1 with NF1, and genes significantly exclusive with actionable driver genes (EGFR, KRAS): MLL2, STK11, KRAS with EGFR." (PMID 35096611, 2021). "The functional significance of NF1 in lung cancer has not been established, but because of its well-known role in many other cancers it is reasonable to assume that it's a driver event in lung cancer as well." (PMID 24722523, 2014). "Two patients (P003 and P006) who met Amsterdam criteria, whose families suffered from colorectal cancer, lung cancer and bladder cancer, were not identified as MMR mutation carriers, but they carried many other tumor-associated genes, such as BRCA2, CDH1, MET, ATM, NF1." (PMID 35372080, 2022). "This case is especially intriguing, as clinical features of NF1 were not recognized until the diagnosis of bilateral PCC was made at age 56 years, and in addition the patient developed primary prostate and lung cancers during his lifetime." (PMID 36760809, 2022). "It remains to be answered whether the development of lung cancer in this young, never-smoker, female patient with NF-1 simply followed the rules of the epidemiology of lung cancer in never-smokers or there is a genetic link between NF-1 and carcinogenesis in the lung." (PMID 23533906, 2013).
astrocytomas (70 papers, 2006 to 2025). "The cell lines used were derived from either an NF1 patient with a malignant astrocytoma or Nf1-deficient mice that spontaneously developed HGGs." (PMID 41294711, 2025). "In this paper, we focus on applications explicitly associated with new developments in the field of NF1, particularly peripheral glial (Schwann cell-derived) and central glial tumors (astrocytomas), which are typically linked to the disease." (PMID 41168866, 2025). "Among circumscribed astrocytic gliomas, Pilocytic AS is characterized by mutations in KIAA1549-BRAF, BRAF, and NF1, while High-Grade Astrocytoma with Piloid Features exhibits alterations in BRAF, NF1, ATRX, and CDKN2A/B (methylome)." (PMID 38534769, 2024). "NF1-associated astrocytomas usually sustain germline mutation of the NF1 gene located on chromosome 17q and somatic loss of the remaining NF1 allele, resulting in bi-allelic inactivation and loss-of-function to the NF1 gene." (PMID 38318325, 2023). "Cases with a PXA morphological diagnosis diverging from the DNA methylation class warrant attention to newer differential diagnoses such as high-grade astrocytoma with piloid features, pilocytic astrocytoma NF1-associated, and NET-PATZ1." (PMID 37998600, 2023). "About 80% of NF1 patients showing optic glioma or astrocytoma were female, carrying mainly frameshift mutations in the NF1 gene (4/8, 50%)." (PMID 35885913, 2022). "In NF1-associated tumors, high-grade astrocytomas in particular have a high prevalence of ATRX mutations and ALT, and these alterations are associated with worse outcomes." (PMID 35740680, 2022). "A GEMM study revealed NF1 as a driver mutation for malignant astrocytoma, contributing to the subsequent discovery of NF1 as a driver mutation in GBM." (PMID 35359410, 2022). "Mutations in CHECK2, EGFR, PTEN, RYR2, and NF1 are instead associated with an IDH1-wildtype astrocytoma." (PMID 34503108, 2021). "While MAPK/ERK activation has been seen across all astrocytoma types, including sporadic and NF1-associated astrocytomas, MAPK/ERK activation in NF1-associated astrocytomas is independent of BRAF alteration." (PMID 31906320, 2020). "In an individual with the NF1 constitutional c.2970_2972del and three astrocytomas, we provided proof that all were NF1-associated tumors given loss of heterozygosity at three intragenic NF1 microsatellite markers and c.2970_2972del." (PMID 30190611, 2019). "A high proportion of astrocytomas from patients with NF1 also demonstrate a loss of neurofibromin expression and a loss of heterozygosity of the NF1 gene." (PMID 24137429, 2013). "Optic glioma (OPG) and astrocytoma were the most NF1-associated nervous system malignancies." (PMID 35885913, 2022).